KLF7 (KLF transcription factor 7)
Diseases named in the same sentence as KLF7 in open-access papers (continued):
Sharing a sentence is not in itself a finding about the gene and the disease.
lung cancer (7 papers, 2021 to 2025). A malignant neoplasm involving the lung. "Overexpression of KLF7 has been associated with worse prognosis in gastric and lung cancers, according to recent studies." (PMID 38909013, 2024). "With the in-depth study of the immune tolerance mechanism of lung cancer, the interaction of KLF7 in the occurrence and development of lung cancer has attracted more and more attention of scholars at home and abroad." (PMID 35936369, 2022). "At present, the study has found that the expression of serum KLF7 in patients with lung cancer is significantly higher than that in healthy people, suggesting that KLF7 is expected to become a new tumor marker." (PMID 35936369, 2022). "In patients with lung cancer, the expression level of serum KLF7 had nothing to do with the gender, age, smoking history, and tumor diameter of patients with NSCLC." (PMID 35936369, 2022). "In lung cancer tissues, KLF7 was significantly higher than that in normal tissue, and associated with tumor size, lymph node metastasis, and clinical stage, and the overall survival rate of patients, indicated that KLF7 as a new prognostic marker or potential therapeutic target." (PMID 38560274, 2024). "Interestingly, miR-103 was found upregulated in non‐small cell lung cancer and promoted cancer progression by directly targeting KLF7." (PMID 35443866, 2022). "For example, KLF7 high expression predicts unfavorable prognosis of lung cancer patients." (PMID 33892667, 2021). "Knockdown of KLF7 inhibits the migration and invasion of lung cancer cells." (PMID 33892667, 2021). "Furthermore, KLF7 can also be targeted by microRNA, such as miR-185 and miR-193a, in lung cancer." (PMID 33892667, 2021). "Among the KLFs, the clear promoting effects on lung cancer were KLF5, KLF7, KLF8, and KLF15, as well as KLF4 and KLF6, which have dual functions." (PMID 38560274, 2024). "The research on the correlation between KLF7 and NSCLC is mainly concentrated in lung cancer tissues and cells, and its research in the serum of lung cancer patients is relatively few." (PMID 35936369, 2022). "The concentration of serum KLF7 in patients with clinical stage IIIa was significantly higher than that in patients with stage I~II, suggesting that KLF7 may have a positive correlation with the degree of malignancy of patients and may have a certain value for the prognosis of lung cancer." (PMID 35936369, 2022).
oral squamous cell carcinoma (6 papers, 2019 to 2025). "Similar prognostic significance of KLF7 expression has been reported in other cancers, including oral squamous cell carcinoma and ovarian cancer." (PMID 38116138, 2023). "KLF7 can also contribute to the migration and epithelial-mesenchymal transition of oral squamous cell carcinoma." (PMID 31552163, 2019). "In this study on oral squamous cell carcinoma (OSCC), we confirmed the key role of KLF7 in maintaining the stemness of OSCC." (PMID 40316546, 2025).
type 2 diabetes (6 papers, 2015 to 2024). "Finally, we show that miR-132-3p overexpression as well as KLF7 downregulation ameliorates EndMT in an in vitro model of diabetes-associated EndMT, thereby identifying both miR-132-3p and KLF7 as novel regulators of aortic stiffening-associated EndMT in type 2 diabetes mellitus." (PMID 36698180, 2023).
non-small cell lung carcinoma (5 papers, 2020 to 2026). A group of at least three distinct histological types of lung cancer, including non-small cell squamous cell carcinoma, adenocarcinoma, and large cell carcinoma. "In a study of acute myeloid leukemia, activated GPR84 can promote disease resistance through the Wnt /β-catenin axis, which targets and modulates the expression of factor KLF7 in non-small cell lung cancer cells." (PMID 37170248, 2023). "And KLF7, regulated by Linc00669/miR-193a axis, may also promote progression of non-small cell lung cancer." (PMID 32677950, 2020). "KLF7, KLF8, and KLF9 contribute to the progression of non-small cell lung cancer (NSCLC) and are the targets of some miRNAs." (PMID 35387557, 2022). "Subsequently, studies suggested that overexpression of KLF7 regulated cell growth and progression by mediating STAT3-induced lncRNA LINC00668 in non-small-cell lung cancer, and contributed to squamous carcinoma progression." (PMID 33858520, 2021).
autism (4 papers, 2021 to 2025). Persistent deficits in social interaction and communication and interaction as well as a markedly restricted repertoire of activity and interest as well as repetitive patterns of behavior. "The largest exon sequencing study on ASD to date (35,584 total samples; 11,986 samples from patients with autism) identified 102 risk genes, and 59 of these risk genes were affected in klf7+/− mice (FDR < 0.01)." (PMID 35328799, 2022). "We compared klf7 target genes with those in the SFARI autism database and found 228 overlapping ASD risk genes." (PMID 35328799, 2022). "Finally, disruptions in KLF7, another identified TF here, have been linked to autism‐like phenotypes in animal models, reinforcing the potential broader impact of DEPDC5‐associated transcriptional changes." (PMID 40704780, 2025). "We constructed klf7−/− mice and then investigated into klf7 regulation on the expression of rhythm genes in vivo as well as the use of melatonin to rescue the autism behavior." (PMID 36207723, 2022). "Our results illustrated that circadian rhythm was disrupted in klf7 knockdown cells and that klf7−/− mice showed autism-like behavior." (PMID 36207723, 2022). "In our recent study, klf7 was confirmed to be an autism-related gene by constructing Nestin-Cre conditional knockout mouse model, though the mechanism behind remains unknown." (PMID 36207723, 2022). "In utero exposure to MIA leads to a downregulated klf7 level in mice at P0, suggesting that there may be a link between environmental exposure, altered klf7 level and the development of autism." (PMID 35328799, 2022). "Klf7 is an important transcription factor of cell proliferation and differentiation in the nervous system, but whether klf7 is involved in autism is unclear." (PMID 35328799, 2022). "Behavioral tests (n = 12 for each group) were performed to determine whether increasing klf7 in klf7+/− adult mice can alleviate autism-like behavior." (PMID 35328799, 2022). "As Klf7 with a 2q33.3q34 deletion has been found to be a candidate gene for Autism, and the patients with this deletion also have microcephaly feature, it is possible that Ln-CR1 could be also involved." (PMID 33760820, 2021). "ChIP-seq of GFP-tagged klf7 in HEK293 cells identified 8692 target genes of human klf7 (GEO accession number: GSM2016749), 264 of which were shared with the Simons Foundation Autism Research Initiative autism database (SFARI, Latest Release: 2021 Q1)." (PMID 35328799, 2022).
breast carcinoma (4 papers, 2022 to 2023). "At present, a research has found that the serum KLF7 level of breast cancer patients is higher than that of healthy people; furthermore, a study has found that the level of serum KLF7 has diagnostic significance for gastrointestinal cancer." (PMID 35936369, 2022). "Using Gene Set Enrichment Analysis of RNA sequencing and proteomical mass spectrometry data in breast cancer cells expressing Krüppel-like factor 7 (KLF7), we identified processes altered by this transcription factor." (PMID 36192788, 2022). "High KLF7 mRNA levels correlated with significantly worse survival in patients, as demonstrated by the mRNA data of 1063 female breast cancer patients (p = 0.045) (data available from v19.3.proteinatlas.org)." (PMID 36192788, 2022). "Nuclear KLF7 expression in breast cancer tissue correlated significantly with the intrinsic subtype (p < 0.001) and tumor grading (p = 0.001), indicating a role in more aggressive cancer types." (PMID 36192788, 2022). "KLF7 was detected not only in the nuclei in breast cancer tissue but also in the cytoplasm, which corroborates observations of the Human Protein Atlas." (PMID 36192788, 2022). "We aimed to elucidate the molecular function of KLF7 in breast cancer and identified a novel and unexpected role of this protein in ribosomal processes and translation." (PMID 36192788, 2022). "Five hundred ninety-seven genes induced in the first 24 h were transcriptional targets of KLF7, which is reported as a tumor suppressor in breast cancer cells." (PMID 35395809, 2022). "In conclusion, we identified a novel link between ribosomal biogenesis and KLF7 in mammary carcinoma." (PMID 36192788, 2022). "Using transcriptomics and proteomics approaches in mammary carcinoma cell lines and in patient tissue samples we aimed at identifying and exploring KLF7 regulated processes." (PMID 36192788, 2022). "We analyzed the expression of KLF7 in human breast cancer tissue in a TMA cohort of 77 female breast cancer patients, derived from primary biopsies." (PMID 36192788, 2022). "We further verified the role of KLF7 the identified ribosomal processes in in vitro assays of mammary carcinoma cell lines and analyses of breast cancer patients’ tissue slices." (PMID 36192788, 2022). "Nuclear KLF7 expression levels correlated significantly with the breast cancer subtypes and grading." (PMID 36192788, 2022). "This confirmed our in vitro data and suggested a role of KLF7 in ribosomal biogenesis in breast cancer tissue." (PMID 36192788, 2022). "We identified the transcription factor Krüppel-like factor 7 (KLF7) as a regulator of ribosomal biogenesis and translation in breast cancer cells and tissue." (PMID 36192788, 2022). "In the Human Protein Atlas, immunohistologic staining of breast cancer tissue with antibody HPA030490 showed a nuclear KLF7 expression of medium to high intensity in > 70% of all patients and in some breast cancer tissue cytoplasmic staining (data available from v19.3.proteinatlas.org)." (PMID 36192788, 2022). "Here, we aimed to identify the yet unknown downstream targets of KLF7 and pinpoint the molecular function of KLF7 in breast cancer." (PMID 36192788, 2022). "In mammary carcinoma, KLF7 is involved in ribosomal biogenesis." (PMID 36192788, 2022). "Here, we investigated the role of KLF7 expression on cellular mechanisms in breast cancer." (PMID 36192788, 2022). "We further identified KLF7 as an important contributor to the aggressiveness of breast cancer." (PMID 36192788, 2022). "Cytoplasmic KLF7 staining has been noticed in breast cancer tissues in the Human Protein Atlas." (PMID 36192788, 2022). "Importantly, in a cohort of breast cancer patients, KLF7-expression levels correlated with aggressiveness of the intrinsic breast cancer subtype and tumor grading." (PMID 36192788, 2022).
breast carcinoma (continued). "We attempted to validate our in vitro findings that KLF7 might regulate ribosomal biogenesis in breast cancer patient samples." (PMID 36192788, 2022). "Therefore, a publicly available dataset from The Cancer Genome Atlas (TCGA) of 1222 breast cancer patients was stratified according to their KLF7 expression level." (PMID 36192788, 2022).
colorectal cancer (4 papers, 2022 to 2024). A primary or metastatic malignant neoplasm that affects the colon or rectum. "In this study, we aimed to investigate the molecular mechanism of Krüppel-like factor 7 (KLF7) in colorectal cancer (CRC) cell invasion and migration." (PMID 39097779, 2024). "Elevated expression of KLF7 in colorectal cancer tissues comparing to adjacent normal tissues has also been reported in previous studies, indicating its relevance in promoting tumorigenesis." (PMID 38116138, 2023). "First, we determined in published microarray data that KLF7 mRNA is significantly upregulated in various subtypes of colorectal cancer." (PMID 36890812, 2023). "Our data indicate that KLF7 may promote the clonogenic activity of colorectal cancer cells and that KLF7 overexpression may even have prognostic value." (PMID 36890812, 2023).
diabetes (4 papers, 2017 to 2024). "Moreover, we demonstrate that miR-132-3p targets KLF7, which is upregulated in an in vitro model of diabetes-associated EndMT, during EndMT-triggered aortic stiffening in db/db mice as well as in aortas of diabetes patients." (PMID 36698180, 2023). "Altogether, this suggests that KLF7 downregulation ameliorates high glucose-induced EndMT in vitro and that miR-132-3p regulates KLF7 in EndMT-triggered diabetes-related aortic stiffening." (PMID 36698180, 2023). "For instance, in research relating to diabetes, KLF7 can directly bind to the promoter region in IL-6 and accelerate the overexpression of IL-6 in inflammatory signaling TLR4/NF-kB/IL-6, thereby causing inflammation." (PMID 35419025, 2022).
ovarian carcinoma (4 papers, 2020 to 2023). A malignant neoplasm originating from the surface ovarian epithelium. "Bioinformatic meta-analysis of six publicly available ovarian cancer transcriptome datasets highlighted KLF7 as the most significant prognostic gene, among the 17 family members, after multiple Cox-regression models corrected for age, FIGO stage and residual tumor after debulking surgery." (PMID 33250051, 2020). "Therefore, targeting KLF7 by small compounds may open new possibilities for ovarian cancer treatment." (PMID 33250051, 2020). "Results from the present study also demonstrated that KLF7 silencing reduces expression and activity of MMP2, a gelatinase shown to be secreted and activated in ovarian cancer and closely correlated with invasion and metastasis of cancer cells and poor survival." (PMID 33250051, 2020).
squamous carcinoma (4 papers, 2020 to 2021). "Our results suggest that KLF7 is expressed at a high level in squamous carcinoma samples and is associated with poor prognosis." (PMID 32536035, 2020). "Log rank test showed a significant difference between the two survival curves (P‐value = 0.012); that is, high KLF7 expression was associated with poor squamous carcinoma prognosis." (PMID 32536035, 2020). "KLF7 was found to be significantly up‐regulated in squamous carcinoma, and the elevated KLF7 expression was obviously associated with poor squamous carcinoma prognosis." (PMID 32536035, 2020). "Elevated KLF7 expression was associated with poor squamous carcinoma prognosis before and after correcting for confounding factors by multivariate Cox regression analysis." (PMID 32536035, 2020). "In conclusion, we consolidate the potential role(s) of KLF7 in squamous carcinoma carcinogenesis from The Cancer Genome Atlas surgical margin tissue, offering insights into expression signatures that are potentially useful for prognosis modalities." (PMID 32536035, 2020). "We examined KLF7 protein levels by immunohistochemistry in 34 matched squamous carcinoma and surgical margin tissues." (PMID 32536035, 2020). "We identified significant up‐regulation of KLF7 in squamous carcinoma, which was confirmed by immunohistochemical staining." (PMID 32536035, 2020). "Multivariate Cox regression analysis determined KLF7 as an independent and robust signature for squamous carcinoma prognosis after correcting for the influences of age, gender, race and stage." (PMID 32536035, 2020). "Second, the pathways involved in KLF7 regulation of squamous carcinoma development remained unclear." (PMID 32536035, 2020). "In this study, the signaling pathways regulated by KLF7 in squamous carcinoma were identified by GSEA, and the three most significant pathways were Neurotrophin signaling pathway, GnRH signaling pathway and long‐term potentiation." (PMID 32536035, 2020). "In the studies on human squamous carcinoma, KLF7 OE was proved to promote migration and induce EMT and lymph node metastasis through the expression of Snail." (PMID 32536035, 2020). "Several pathways, such as Neurotrophin and GnRH pathways, were activated in KLF7‐up‐regulated squamous carcinoma samples through Gene Set Enrichment Analysis." (PMID 32536035, 2020). "In this study, we reported the role of KLF7 in squamous carcinoma through comprehensively analyzing gene expression profiles from squamous carcinoma and surgical margin in The Cancer Genome Atlas (TCGA)." (PMID 32536035, 2020). "In this study, the expression of KLF7, one of the regulators of cell proliferation and differentiation in several different organ systems, was found to be significantly up‐regulated in squamous carcinoma tissues compared with surgical margin." (PMID 32536035, 2020). "Here, we evaluated the potential of Krüppel‐like factor 7 (KLF7) as a prognostic signature in squamous carcinoma." (PMID 32536035, 2020). "Mann–Whitney U test displayed significantly elevated expressions of KLF7 in squamous carcinoma samples compared with surgical margin (P‐value = 3.07e−11)." (PMID 32536035, 2020). "Elevated KLF7 contributes to the progression of squamous carcinoma." (PMID 33892667, 2021). "Moreover, our data suggest that several pathways, such as the Neurotrophin and GnRH pathways, are activated in squamous carcinoma samples with high levels of KLF7." (PMID 32536035, 2020). "Therefore, we speculated that the KLF7/GnRH/JNK pathway might participate in the regulation of squamous carcinoma stem cells." (PMID 32536035, 2020). "Therefore, it could be speculated that the elevated expression of KLF7 might be able to promote the proliferative and survival behavior of squamous carcinoma cells in the nerve environment and mediate the cellular interactions with nerve." (PMID 32536035, 2020).
squamous carcinoma (continued). "Finally, KLF7 was found to be broadly expressed at low levels in adult tissues, and its expression could be regulated by miR‐185; this study was expected to contribute to the crafting of epigenetic therapeutic strategies for squamous carcinoma." (PMID 32536035, 2020). "The result of RT‐qPCR also demonstrated that high KLF7 mRNA expression could enhance the GnRH mRNA expression in SCC9 and CAL27 squamous carcinoma." (PMID 32536035, 2020). "Therefore, the role of KLF7 during the development of squamous carcinoma is not clear." (PMID 32536035, 2020).
acute lymphoblastic leukemia (3 papers, 2014 to 2025). Leukemia with an acute onset, characterized by the presence of lymphoblasts in the bone marrow and the peripheral blood. "Elevated levels of the transcription factor KLF7 is associated with minimal residual disease and relapse following chemotherapeutic treatment of childhood acute lymphoblastic leukemia (ALL) and KLF7 also promote early T cell survival." (PMID 24886479, 2014). "Increased expression of Klf7 has been shown to enhance the survival of early thymocytes and is a predictor of poor outcomes in acute lymphoblastic leukemia." (PMID 40326866, 2025). "For example, KLF7 serves as an independent predictor of poor prognosis in pediatric acute lymphoblastic leukemia, where enhanced expression of KLF7 inhibited hematopoietic stem and progenitor cell function." (PMID 33858520, 2021).